XPO1 (exportin 1)
Diseases named in the same sentence as XPO1 in open-access papers (continued):
Sharing a sentence is not in itself a finding about the gene and the disease.
non-Hodgkin lymphoma (4 papers, 2016 to 2023). Distinct from Hodgkin lymphoma both morphologically and biologically, non-Hodgkin lymphoma (NHL) is characterized by the absence of Reed-Sternberg cells, can occur at any age, and usually presents as a localized or generalized lymphadenopathy associated with fever and weight loss. "This is especially relevant for non-Hodgkin lymphoma (NHL), where high XPO1 expression is associated with poor prognosis due to its oncogenic role in exporting proteins and RNA that are involved in cancer progression and treatment resistance." (PMID 36671496, 2023). "We then highlight the research to date on XPO1 inhibitors such as selinexor and other selective inhibitors of nuclear export (SINEs), which are used to treat some cases of non-Hodgkin lymphoma." (PMID 36671496, 2023). "The first-in-class inhibitor of exportin-1 (XPO1) selinexor is currently under clinical investigation in combination with the BTK inhibitor ibrutinib for patients with chronic lymphocytic leukaemia (CLL) or non-Hodgkin lymphoma." (PMID 37528310, 2023). "In previous studies we demonstrated that targeting the nuclear exporter protein exportin-1 (CRM1/XPO1) by a selective inhibitor of nuclear export (SINE) compound is a viable therapeutic strategy against Non-Hodgkin Lymphoma (NHL)." (PMID 27693556, 2016).
non-small cell lung carcinoma (4 papers, 2014 to 2026). A group of at least three distinct histological types of lung cancer, including non-small cell squamous cell carcinoma, adenocarcinoma, and large cell carcinoma. "In addition, PUS1 may participate in DNA repair, E2F targeting, MYC targeting, and the G2M checkpoint and promote malignant transformation in non-small cell lung cancer (NSCLC) through mcm5 or XPO1." (PMID 41501031, 2026).
bladder cancer (3 papers, 2023 to 2025). "We have reported that COP represses the malignant biological behaviors of bladder cancer cells via repressing the expression of exportin-1 (XPO1)." (PMID 41287122, 2025). "We previously reported that COP represses the malignant biological behaviors of bladder carcinoma cells and regulates XPO1 expression." (PMID 41287122, 2025). "We also verified the relationship between one of the hub genes (XPO1) expression and prognosis in bladder cancer tissue specimens by immunohistochemistry (IHC)." (PMID 37601252, 2023). "In order to verify the relationship between seven hub genes and the prognosis of clinical patients with bladder cancer, we selected XPO1 gene as the target gene to detect the expression in pathological samples of patients with bladder cancer." (PMID 37601252, 2023). "At the same time, we verified that one of hub genes XPO1 has an important effect on the treatment of bladder cancer." (PMID 37601252, 2023). "And it demonstrated that Selinexor, an inhibitor of XPO1, inhibited bladder cancer cell lines and also inhibited growth of transplanted tumor from M49 bladder cancer cell line." (PMID 37601252, 2023). "The expression of XPO1 in bladder cancer tissues was significantly higher than that in normal tissues." (PMID 37601252, 2023). "And XPO1 is an important target affecting the prognosis of bladder cancer, and inhibition of XPO1 can effectively inhibit bladder cancer proliferation and growth." (PMID 37601252, 2023). "In bladder cancer, we screened seven hub genes (ACLY, CNP, NKIRAS2, P3H4, PDIA6, VPS25 and XPO1) associated with survival." (PMID 37601252, 2023). "Considering the relationship between XPO1 and tumor immunity, we selected not only several human bladder cancer cell lines (T24, HT1376), but also murine cell line MB49 as experimental materials." (PMID 37601252, 2023). "The best cut-off value was used to classify high and low XPO1 expression values, and the K–M curve showed that patients with high XPO1 expression had shorter survival in the external bladder cancer cohort." (PMID 37601252, 2023). "Our results are consistent with previous reports that XPO1 is weakly expressed in normal bladder tissues and highly expressed in bladder cancer." (PMID 37601252, 2023). "Immunohistochemical results basically confirmed the importance of XPO1 in bladder cancer." (PMID 37601252, 2023). "Besides, the prognostic value of XPO1 was validated in 165 bladder cancer samples from the GSE13507 cohort of the GEO database." (PMID 37601252, 2023). "Selinexor (an inhibitor of XPO1) could effectively inhibit the proliferation of bladder cancer in the cell proliferation experiments by CCK-8 assays and it could suppress the growth of bladder cancer in mouse bladder cancer model." (PMID 37601252, 2023). "Moreover, the expression level of XPO1 in advanced stages of bladder cancer was higher than that in lower stages." (PMID 37601252, 2023). "In addition, ACLY, NKIRAS2, XPO1 and tumor purity were significantly positively correlated (p < 0.001), which further indicates that ACLY, NKIRAS2 and XPO1 may be potential targets for the treatment of bladder cancer." (PMID 37601252, 2023). "To further verify the inhibitory effect of XPO1 on bladder cancer, we examined the inhibitory effect of Selinexor, an inhibitor of XPO1, on murine bladder cancer cell lines MB49 and human bladder cancer cell lines T24 and HT1376." (PMID 37601252, 2023).
cholangiocarcinoma (3 papers, 2017 to 2025). A carcinoma that arises from the intrahepatic biliary tree (intrahepatic cholangiocarcinoma) or from the junction, or adjacent to the junction, of the right and left hepatic ducts (hilar cholangiocarcinoma). "We found that XPO1 inhibition by KPT‐330 significantly disrupted cholangiocarcinoma cell proliferations." (PMID 36200270, 2023). "We analyzed the prognosis of 30 patients with cholangiocarcinoma using GSE107943 from the GEO database and the results showed that higher expression of XPO1 was significantly associated with poor patient prognosis in CHOL." (PMID 36200270, 2023). "CCK‐8 assays showed that overexpression of XPO1 significantly promoted the proliferation of cholangiocarcinoma cells." (PMID 36200270, 2023). "Based on bioinformatics analysis, we performed basic experiments to verify the effect of XPO1 on cholangiocarcinoma tumor cells." (PMID 36200270, 2023). "Based on previous bioinformatics analysis, we screened the protein BIRC6, which may affect the progression of cholangiocarcinoma cells with XPO1." (PMID 36200270, 2023). "In addition, the colony formation assay indicated that XPO1 overexpression significantly increased the number and size of colonies formed by cholangiocarcinoma cells." (PMID 36200270, 2023). "Therefore, XPO1 may be a potential therapeutic target in cholangiocarcinoma, mediated by its effects on KPT‐330." (PMID 36200270, 2023). "We used XPO1 overexpression plasmid in RBE and 9810 cells to investigate the effect of XPO1 on cholangiocarcinoma cell proliferation." (PMID 36200270, 2023). "However, the role of XPO1 and its therapeutic effect on KPT‐330 on cholangiocarcinoma has yet to be elucidated." (PMID 36200270, 2023). "Therefore, XPO1 may be a potential therapeutic target, and KPT‐330 may play a therapeutic role in cholangiocarcinoma." (PMID 36200270, 2023).
endometrial cancer (3 papers, 2018 to 2024). Primary or metastatic malignant neoplasm involving the endometrium (mucous membrane that lines the endometrial cavity). "Recent studies have pointed out that selinexor (an approved inhibitor of XPO1-mediated nuclear export) plus chemotherapy was a safe and tolerated treatment in advanced ovarian and endometrial cancer patients." (PMID 36589683, 2022).
esophageal cancer (3 papers, 2022 to 2025). A primary or metastatic malignant neoplasm involving the esophagus. "We discovered 21 active novel compounds against esophageal cancer and identified a novel XPO1 inhibitor verdinexor as a new targeted anti-esophageal cancer drug." (PMID 34975332, 2022). "Taken together, verdinexor inhibited cell proliferation and migration of esophageal cancer via XPO1/c-Myc/FOSL1 axis." (PMID 34975332, 2022). "In conclusion, verdinexor inhibits the proliferation and migration of esophageal cancer via the XPO1/c-Myc/FOSL1 axis." (PMID 34975332, 2022). "Verdinexor inhibits cell survival and migration of esophageal carcinoma via the XPO1/c-Myc/FOSL1 axis." (PMID 34975332, 2022). "In this study, we first proved that inhibition of XPO1 has an anti-esophageal cancer effect." (PMID 34975332, 2022). "Similarly, in this study, we found that XPO1 mRNA was overexpressed in esophageal carcinoma compared to normal samples." (PMID 34975332, 2022). "Furthermore, we investigated the expression of XPO1 in three cases of esophageal carcinoma and normal esophageal tissues." (PMID 34975332, 2022). "To explore potential anti-esophageal cancer drugs, we conducted drug screening and discovered that verdinexor, a selective inhibitor of nuclear exportin 1 (XPO1/CRM1), has anti-esophageal cancer effects both in vivo and in vitro." (PMID 34975332, 2022).
high-grade gliomas (3 papers, 2018 to 2021). "Collectively, these results suggest that inhibition of XPO1 and Bcl-2/Bcl-xL might be a potential strategy for the treatment of malignant glial tumors." (PMID 30337641, 2018).
lung adenocarcinoma (3 papers, 2019 to 2024). A carcinoma that arises from the lung and is characterized by the presence of malignant glandular epithelial cells. "Previously, a general dependency of KRAS-mutated NSCLC on XPO1 was reported, and Selinexor monotherapy reduced tumor growth in multiple patient-derived lung adenocarcinoma xenografts." (PMID 38756650, 2024). "This case involved the discovery of the XPO1-ALK fusion and demonstrated that a patient with multiple organ metastases and lung adenocarcinoma harboring an XPO1-ALK fusion mutation responded effectively to brigatinib targeted therapy without serious adverse effects that could cause dosing changes." (PMID 39911820, 2024). "According to the TCGA database, XPO1 and NMD3 genes are frequently altered in lung squamous cell carcinoma and to a less extent in lung adenocarcinoma." (PMID 31113936, 2019).
myocardial infarction (3 papers, 2019 to 2024). Gross necrosis of the myocardium, as a result of interruption of the blood supply to the area, as in coronary thrombosis. "Knockdown of XPO1 expression attenuated cardiac dysfunction and remodeling in animal models after myocardial infarction." (PMID 38669428, 2024). "This study offers a new way to restore cardiac function in patients who have suffered from myocardial infarction, by gene therapy through the silencing of XPO1." (PMID 31768947, 2020). "In conclusion, AAV9-shXPO1 administration attenuates cardiac dysfunction in rats after myocardial infarction, producing the gene silencing of XPO1." (PMID 31768947, 2020). "AAV9-shXPO1 administration attenuates cardiac dysfunction and remodeling in rats after myocardial infarction, producing the gene silencing of XPO1." (PMID 31768947, 2020).
rectal cancer (3 papers, 2018 to 2021). A primary or metastatic malignant neoplasm that affects the rectum. "An XPO1 inhibitor has proven to radiosensitize rectal cancer cells and GBM cells both in vitro and in vivo." (PMID 32612949, 2020). "In a preclinical rectal cancer model, inhibition of exportin 1, a mediator for the nuclear export of critical proteins required for rectal cancer proliferation and treatment resistance, resulted in an increased apoptosis and decreased proliferation under single irradiation." (PMID 30112378, 2018).
anaplastic thyroid cancer (2 papers, 2019 to 2024). "Nonetheless, we have demonstrated the therapeutic relevance of targeting nuclear export protein XPO1 and Rho GTPase effector PAK4 which has possible implications in overcoming lenvatinib therapy resistance in anaplastic thyroid cancer." (PMID 31905765, 2019). "In conclusion, our studies bring forward two novel targets XPO1 and PAK4 as actionable therapeutic avenues to overcome resistance to lenvatinib in refractory anaplastic thyroid cancer." (PMID 31905765, 2019). "We next explored the impact of targeting nuclear exporter protein XPO1 and Rho GTPase effector PAK4 either alone or in combination with lenvatinib in anaplastic thyroid cancer cells." (PMID 31905765, 2019). "Therefore, it may be envisaged that targeting XPO1 by SINE or PAK4 by KPT-9274 may serve to reduce the dose and frequency of lenvatinib regimen required to achieve therapeutic effects in anaplastic thyroid cancer." (PMID 31905765, 2019). "Furthermore, we showed that targeted inhibition of XPO1 and PAK4 could sensitize anaplastic thyroid cancer cells to lenvatinib." (PMID 31905765, 2019).
atherosclerosis (2 papers, 2023 to 2025). A disease characterized by the build-up of fatty material and calcium deposition in the arterial wall resulting in partial or complete occlusion of the arterial lumen. "Additionally, XPO1 and POU2F1 were involved in human T-cell leukemia virus 1 and lipid and atherosclerosis signaling pathways, respectively." (PMID 37370118, 2023).
benign lipoma (2 papers, 2017 to 2021). "In contrast, very weak or negative immunoreactivity of XPO1 was observed in benign lipoma tissues." (PMID 27893412, 2017).
bladder tumor (2 papers, 2018 to 2023). "The bladder tumor tissue array consisting of 53 high grade urothelial carcinomas was used to determine XPO1 expression." (PMID 30349650, 2018). "A review of Oncomine datasets identified two studies which showed highly statistically significant increases of XPO1 expression in bladder tumors when compared with control tissue." (PMID 30349650, 2018). "While all the bladder tumor cells tested were sensitive to selinexor treatment, T24 and UM-UC-3 cells, which express wt RB, exhibited a heightened response to XPO1 inhibition." (PMID 30349650, 2018). "In this study we assessed selinexor-dependent cytotoxicity in several bladder tumor cells and report that selinexor effectively reduced XPO1 expression and limited cell viability in a dose dependent manner." (PMID 30349650, 2018). "The current study focused on bladder malignancies and showed by data mining and tumor tissue array analysis that XPO1 is elevated in bladder tumor cells." (PMID 30349650, 2018). "We accessed XPO1 expression in 13 bladder tumor patient derived xenografts generated from high grade malignancies that were established by our colleagues at UC Davis." (PMID 30349650, 2018). "Conversely, limiting CDK4/6 dependent RB phosphorylation by palbociclib was additive with selinexor in reducing bladder tumor cell viability, confirming that RB activity has a role in the response to XPO1 inhibition." (PMID 30349650, 2018). "Cultured bladder tumor-derived cells have higher XPO1 levels than immortalized SV-HUC1 cells." (PMID 30349650, 2018).
Chronic myeloid leukemia (2 papers, 2020 to 2024). "Results from GSEA showed that XPO1 activated KEGG Pathways in cancer, KEGG_Ubiquitin mediated proteolysis, KEGG_Cell cycle, KEGG_Spliceosome, and KEGG_Chronic myeloid leukemia." (PMID 39177040, 2024). "Other examples of tumor- specific cargoes are nuclear export of cyclin D1 mRNA in MCL, with decreased cyclin D1 levels upon inhibition of XPO1, and BCR-ABL in chronic myeloid leukemia (CML), as elaborated below." (PMID 32624581, 2020).
COVID-19 (2 papers, 2021 to 2022). A disease caused by infection with severe acute respiratory syndrome coronavirus 2. "In addition to its role in tumors, XPO1 is also crucial for COVID-19 infection, with selinexor recently shown to inhibit COVID-19 mediated pathology and neutrophilic rhinitis." (PMID 34926302, 2021).
cutaneous T-cell lymphoma (2 papers, 2024 to 2025). "In this study, we exhibited the pre-clinical therapeutic effectiveness of KPT-330, a selective inhibitor of XPO1, in cutaneous T-cell lymphoma (CTCL) cells." (PMID 38653804, 2024). "In summary, our study underscores the therapeutic promise of KPT-330, an XPO1 inhibitor, for treating cutaneous T-cell lymphoma (CTCL)." (PMID 38653804, 2024). "In human cutaneous T-cell lymphoma, the downregulation of survivin, a key inhibitor of apoptosis, following XPO1 inhibition may lower the cellular threshold for apoptosis, enhancing the drug sensitivity." (PMID 40872651, 2025).
fibrosarcoma (2 papers, 2020 to 2024). A malignant mesenchymal fibroblastic neoplasm affecting the soft tissue and bone. "The in vitro production of selinexor-resistant fibrosarcoma cell lines did not reveal the emergence of mutations, suggesting that in fibrosarcoma, resistance to XPO1 inhibition is not due to mutation of the target which could prevent the binding of the drug." (PMID 39050883, 2024).
head and neck cancer (2 papers, 2023 to 2024). A primary or metastatic malignant neoplasm affecting the head and neck. "Gene therapy approaches such as siRNA-mediated knockdown of XPO1 and CRISPR-Cas9 technology have also shown promise in preclinical models of head and neck cancer." (PMID 38820302, 2024).
head and neck squamous cell carcinoma (2 papers, 2024 to 2025). A squamous cell carcinoma that arises from any of the following anatomic sites: lip and oral cavity, nasal cavity, paranasal sinuses, pharynx, larynx, and salivary glands. "Experimental studies suggest that there is a synergistic effect between Exportin 1 inhibitors and anthracyclines in head and neck squamous cell carcinomas, i.e., Exportin 1 inhibition can reverse anthracycline resistance." (PMID 40001478, 2025).
hearing loss (2 papers, 2023 to 2024). "For almost all traits, except IUGR and hearing loss, our analysis pinpointed at least two SROs including the BCL11A, and the USP34 and XPO1 genes, respectively." (PMID 36807877, 2023). "Moreover, patients feature phenotypes, including hearing loss, intrauterine growth restriction, and short stature, that cannot be delineated to variations in the BCL11A gene but are associated with USP34 (ubiquitin specific peptidase 34) and XPO1 (exportin 1), two candidate genes in close proximity." (PMID 38392344, 2024).
ischemic cardiomyopathy (2 papers, 2020 to 2024). Ischemic cardiomyopathy is a cardiomyopathy in which a weakness in the muscle of the heart due to inadequate oxygen delivery to the myocardium with coronary artery disease being the most common cause. "The transcriptomic signature of these alterations has been found and has been identified that changes in gene expression, specifically of XPO1 that encodes EXP-1, were highly related to LV dysfunction in patients with ischemic cardiomyopathy." (PMID 31768947, 2020). "Transcriptomic signature of XPO1 was highly expressed and inversely related to left ventricular function in ischemic cardiomyopathy patients." (PMID 31768947, 2020). "Previous studies have shown that several molecules that participate in nuclear-cytoplasmic transport (Exportin-1 [EXP-1], IMP-β3, Nup160) are intimately related to a reduced left ventricular (LV) function in human ischemic cardiomyopathy." (PMID 31768947, 2020).